IL1B (interleukin 1 beta)
Diseases named in the same sentence as IL1B in open-access papers (continued):
Sharing a sentence is not in itself a finding about the gene and the disease.
Sepsis (continued). "It was found that the expressions of TNF-α, IL-1β, IL-6 in CLP group were significantly increased (P < 0.001), suggesting that animal’s inflammatory response was activated by sepsis." (PMID 34565302, 2021). "Cytokine secretion mediates brain dysfunction, and the increases of IL-1β, IL-6, and TNF-α are involved in cognitive impairment after sepsis." (PMID 35111693, 2021). "The proinflammatory response in the acute phase of sepsis eliminates invading pathogens and involves immunocyte activation and subsequent production of cytokines such as TNF-α, IL-1β, and IL-6." (PMID 34907156, 2021). "Overall, all patients had elevated TNF-a and IL-6 levels at initial screening, and most had elevated IL-1β and IL-18, while some had elevated IFN-γ; however, a gradual decrease in levels of all of the cytokines studied was observed upon resolution of sepsis." (PMID 34659208, 2021). "The relationship between sepsis and increased levels of proinflammatory cytokines such as TNF-α and IL-1β is known as a mechanism for eliminating invading pathogens." (PMID 34499695, 2021). "The results showed that at 6 h after sepsis, except for IL-6, TNF-α, IL-1β, and IL-10 levels decreased in DEX-treated mice." (PMID 33981237, 2021). "Compared with those in the CLP + DEX group, the levels of TNF-α, IL-1β, and IL-10 increased significantly in the CLP group at 6 h after sepsis induction." (PMID 33981237, 2021). "The expression level of MALAT1 was significantly increased in sepsis in vitro, and MALAT1 knockout also reduced serum levels of cTn-I, TNF-α, IL-1β, IL-6, IL-10, IL-17, IFN-γ, C5, and C5a." (PMID 34514170, 2021). "To further explore the proinflammatory effects of MSN in sepsis, we next performed ELISA to measure the effects of MSN silencing on the production of the inflammatory cytokines TNF-α, IL-6, IL-1β, and IL-18 in medium supernatant of HMECs." (PMID 33628853, 2021). "The protein and mRNA expressions of IL-1β, IL-6, and TNF-α were all markedly elevated in renal tissue of mice with CLP-induced sepsis, which were consistent with findings from other studies." (PMID 34187277, 2021). "Here, we show that cardiac function and structure deteriorates during sepsis and that inhibition of NLRP3/IL‐1β improves both entities." (PMID 34472725, 2021). "It has been reported that serum cytokines such as IL-1β, IL-6, IL-8, IL-10, IL-12, IL-17A, IL-18, interferon gamma (IFN-γ), and TNF-α are elevated in sepsis, but some of these cytokines are also elevated in FMF patients." (PMID 34654467, 2021). "Attenuation of sepsis-induced acute kidney injury was due to the prohibited production of inflammatory cytokines and decrease expression of Caspas-1, NLRP-1, IL-1β, and IL-18 in renal tissues." (PMID 34222479, 2021). "To determine if gestational sepsis induces upregulation of cytokine up in neonates, we analyzed the levels of TNF-α, IL-1β, and IL-6 in the liver, lung, and brain of neonates at P2 and P8." (PMID 33632243, 2021). "Our results showed that either LPS injection or CLP surgery significantly up‐regulated the levels of circulating TNF‐α, IL‐1β, IFN‐γ and IL‐6 in mice, indicating successful establishment of sepsis mouse model." (PMID 33982381, 2021). "We previously found that IL-1β-activated MSCs upregulated CXCR4 expression, promoted their migration to inflammatory sites, and improved the symptoms of sepsis in mice." (PMID 34627385, 2021). "This study showed that sepsis patients have increased expression of five platelet proteins: EFCAB7 (calcium ion binding), actin (cytoskeleton), IL-1β (cytokine), GPIX (membrane receptor), and GPIIb (integrin)." (PMID 34745104, 2021). "Numerous studies demonstrated that the excessive release of proinflammatory cytokines, such as IL-1β, IL-6, and TNF-α, triggered the pathophysiological abnormities of sepsis and played prominent roles in septic AKI." (PMID 33511217, 2021).
Sepsis (continued). "Multiple studies have shown that the levels of inflammation-related factors in serum are directly proportional to the severity of sepsis, such as TNF-α, IL-6, and IL-1β." (PMID 33710444, 2021). "Cardiodepressant inflammatory cytokines, particularly interleukin‐1β (IL‐1β) and tumour necrosis factor (TNF), are significantly increased during sepsis in both patients and animal models." (PMID 34472725, 2021). "We measured the pro-inflammatory cytokine levels (IL-1β, IL-6, TNF-α) in the plasma and hippocampus to evaluate central and peripheral inflammation during the acute phase of sepsis in SAMP8 and SAMR1." (PMID 33643027, 2021). "NF-κB participates in the development of sepsis by enhancing the transcription of proinflammatory cytokines, such as TNF-α, IL-6, and IL-1β." (PMID 34616305, 2021). "Cardiac dysfunction and inflammation were observed in sepsis rat, which were characterized by the decrease of LVSP and + dp/dtmax, the increase of LVEDP, − dp/dtmax, cTnI, CK-MB, TNF-α, IL-1β, IL-6." (PMID 34376255, 2021). "Macrophages treated with LPS in the presence of CaD expressed significantly lower IL1β, TNFα, and MCP-1, in agreement with a previous study where CaD reduced pro-inflammatory cytokine production in a rat model of sepsis." (PMID 34829669, 2021). "In a neonatal murine E. coli sepsis model, IL-27Rα-/- mice showed lower levels of TNF-α, IL-1β and IL-6, and improved survival rates." (PMID 34079555, 2021). "AKI in sepsis is accompanied by systemic inflammation and the excessive production of pro-inflammatory cytokines including TNF-α, IL-6, and IL-1β." (PMID 33841147, 2021). "Sepsis/endotoxemia activates the NLRP3 inflammasome of macrophages leading to the maturation and release of IL-1β, an important mediator of the inflammatory response." (PMID 33101273, 2020). "Compared with other early -phase pro-inflammatory contents, for instance tumor necrosis factor (TNF) and IL-1β, HMGB1 began to appear 8 h and significantly increased after initiation of sepsis." (PMID 33552058, 2020). "At the early stage of sepsis, activated macrophages release a large amount of pro-inflammatory cytokines such as TNF-α, IL-1β, IL-6 to resolve invading pathogens and injured tissues, playing pivotal role in host defense." (PMID 32415087, 2020). "The results obtained showed that the rats in the untreated sepsis group showed significantly elevated levels of pro-inflammatory cytokines (IL-1α, IL-2, TNF-α, IL-6, IFN-γ, IL-1β) in plasma." (PMID 32076015, 2020). "A cytokine array found that the QX1 formula attenuated sepsis-induced upregulated levels of serum IFN-γ, IL-1β, IL-3, IL-6, IL-17, IL-4, IL-10, and TNF-α." (PMID 32908632, 2020). "Since the deficiency of NLRP3-IL-1β pathway prevented chronic, but not acute, neuroinflammation after sepsis, we next studied whether blockage of generation or action of IL-1β would avoid sepsis-associated neurodegeneration once acute neuroinflammation began." (PMID 32070376, 2020). "After knockdown ofmiR-451a, the increased levels of IL-1β, IL-6 and TNF-α were reduced significantly(all P < 0.01), indicating that the inhibition of miR-451a in sepsis led to suppressedinflammation." (PMID 33211058, 2020). "A feed-forward mechanism for IL-1β generation exists, i.e., IL-1β can activate the NLRP3 inflammasome and vice versa, representing a potential mechanism of generating the exaggerated cytokine response in sepsis." (PMID 33101273, 2020). "Following sepsis induction by CLP, the pro-inflammatory cytokines, IL-1β, IL-6, tumor necrosis factor (TNF)-α, and monocyte chemoattractant protein (MCP)-1, showed a marked increase." (PMID 32943679, 2020). "GTS-21, a synthetic selective stimulant of α7nAchR, has been shown to reduce myocardial injury via modulating inflammation (decreases in IL-6, IL-1β, TNF-α and activation of NF-κB P65) and apoptosis in LPS-induced sepsis in mice." (PMID 32194424, 2020).
Sepsis (continued). "During sepsis, HIF-1α, stimulated by LPS, activates the generation of inflammatory cytokines (including TNF-α, IL-1β and IL-6) and proapoptotic proteins, leading to inflammation and apoptosis." (PMID 32353952, 2020). "The levels of pro-inflammatory cytokines, including tumor necrosis factor (TNF)-α, IL-1β, IL-6, and MCP-1, have been observed to increase in the myocardium in response to sepsis." (PMID 32256344, 2020). "We then examined the serum levels of inflammatory cytokine TNF-α, IL-6, IL-1β, and IL-10, and the clinical markers of acute systemic inflammation MCP-1 and CRP by ELISA in LPS-induced sepsis model." (PMID 32457606, 2020). "Levels of inflammatory markers like tumor necrosis factor-alpha (TNF-α), interleukin-1-beta (IL-1β) and, interleukin-6 (IL-6) as well as VEGF, a specific sepsis marker in plasma, were quantified." (PMID 33371296, 2020). "In a clinical study, the levels of IL-1β, IL-6, TNF-α, etc., except for IL-10, were inhibited in the late phase of sepsis, while, in an animal study, the immune suppression status was attenuated with administration of the adenovirus Ade-HIF-1α." (PMID 32089644, 2020). "The expression levels of TNF-α, IL-6, and IL-1β were significantly increased inthe CLP group compared with the sham group, indicating that sepsis promotedinflammation." (PMID 32578720, 2020). "In the sepsis+MLD group, the mRNA expression of TNF-α, IL-1β, and IL-6 in the lung was significantly decreased, compared with the sepsis group (p < 0.05)." (PMID 33145344, 2020). "It was reported that in mice, quercetin protects mice from LPS-induced sepsis by inhibiting proinflammatory cytokine TNF-α and IL-1β expression, NF-κB activation, and apoptosis." (PMID 32908632, 2020). "The detection of inflammatory mediators of each group showed that LPS significantly increased the levels of TNF-α, IL-6, IL-1β, and MCP-1, and decreased the level of IL-10, consistent with those results discovered in mice with sepsis-induced kidney injury." (PMID 33197894, 2020). "We found that the levels of IL-6, TNF-α, IL-1β, and MCP-1 were significantly increased at 24 h after sepsis." (PMID 32273831, 2020). "As an early signaling activated in sepsis, NF-κB activates the transcription of a series of proinflammatory cytokines to activate cytokine storm in septic shock, including TNF-α, IL-1β, and IL-12." (PMID 33986658, 2020). "We also analyzed five other well-known sepsis markers across all available time points: procalcitonin, C-reactive protein (CRP), granulocyte colony-stimulating factor (G-CSF), IL-1β, and IL-8, as measured by a commercial bead-based immunoassay (see “Methods”)." (PMID 32451375, 2020). "The researchers also observed that the levels of IL-1β, IL-6, IL-10, MCP-1, and TNF-α were significantly increased in septic shock as compared with severe sepsis." (PMID 32153410, 2020). "Treatment with an IκB kinase inhibitor attenuated sepsis-induced cardiac dysfunction with chronic kidney disease (CKD) via reduced expression of inflammatory cytokines (TNF-α, IL-1β, IL-6, and IL-10)." (PMID 32581829, 2020). "In both groups (isoflurane and Propofol), exposure to cecal ligation and puncture (CLP)/sepsis-inflammation led to increased fluid requirements, lower MAP at 8 h, development of a base deficit, and increased interleukins (IL-6, IL-1β, and TNF-α) at 8 h." (PMID 33392215, 2020). "IL-1β and IL-18 are crucial activation elements of the NLRP3 inflammasome during pyroptosis, and their production is known to be activated by I/R and sepsis but suppressed by propofol." (PMID 33260147, 2020). "For this purpose, we used antagomir-21 to inhibit miR-21 expression in murine sepsis model and detected the levels of proinflammatory cytokines (TNF-α, IL-1β, and IL-6), liver injury markers (AST, ALT), and PPARα expression." (PMID 33424957, 2020).
Sepsis (continued). "The nucleotide-binding oligomerization domain-like receptor with pyrin domain (NLRP3) inflammasome and IL-1β have been shown to be expressed at high levels in a cecal ligation and puncture (CLP) sepsis model." (PMID 32581829, 2020). "Both sepsis groups had higher gene expressions of NLRP3, caspase-11, and IL-1β and lower expression of IL-18 compared to the sham group." (PMID 32295272, 2020). "In the ileal tissues of healthy mice, sepsis EVs (S-EVs) downregulated messages of the pro-inflammatory cytokines including TNF-α, IL-1β, IL-6, IL-17A, and IL-22." (PMID 33182773, 2020). "Serial monitoring of serum CRP, PCT, IL-6, IL-1b, sIL-2R, and LBP after death has been suggested to be helpful for the postmortem diagnosis of sepsis, but more studies are needed." (PMID 31661804, 2019). "In order to further investigate the effects of miR-106a on sepsis, we selected three cellular inflammatory factors TNF-α, IL-1β, IL-6 as representatives for research." (PMID 31432993, 2019). "Other evidence has indicated that miR-23b plays crucial roles in the pathomechanism of sepsis by suppressing the production of inflammatory cytokines, including NF-κB, TNF-α, IL-6, IL-1β, and E-selectin." (PMID 31780861, 2019). "EP downregulated the expression of multiple proinflammatory proteins, including IL-1β, TNF-α, and HMGB1 in animal experiments of endotoxemia and sepsis." (PMID 31933629, 2019). "Serum cytokines, including IL6, IFNγ, IL1β, IL10, and TNFα were high suggesting the onset of sepsis in most of these mice even though there was a high degree of variation of bacterial load." (PMID 31121001, 2019). "Because regulatory T cells are thought to involve in immuno-paralysis in the late phase of sepsis, we have attempted to measure expression of FoxP3 in the CD4 T cells proliferated or skewed by IL-1β." (PMID 31323786, 2019). "Erastin administration increased the survival rate in mice upon sepsis induction, followed by a reduction in inflammatory mediators and cytokines, including NO, TNF-α, and IL-1β." (PMID 31847346, 2019). "Post hoc comparisons showed that the expressions of IL-1β and TNF-α were markedly increased in sepsis mice at 24 h following CLP (all p < 0.01), whereas clenbuterol treatment markedly decreased these inflammatory mediators (all p < 0.01)." (PMID 31354429, 2019). "During inflammation and sepsis, plasma C-reactive protein (CRP), IL-6, IL-1β, and TNF-α levels in the circulatory system are increased." (PMID 31835381, 2019). "The levels of leptin seem to rapidly increase in acute inflammatory conditions, such as cholecystectomy and sepsis, particularly favored by cytokines such as TNF-α, IL-6, and IL-1β." (PMID 30949073, 2019). "During the course of polymicrobial sepsis excessive production of proinflammatory cytokines, e.g., TNF or IL-1β, is dependent on IFNAR-mediated signaling." (PMID 31500303, 2019). "While little information about this exists, our data show that sepsis-triggered canonical inflammasome depends on the NLRP3/caspase-1 pathway for the maturation and secretion of IL-1β and on GSDMD for the induction of pyroptosis." (PMID 30276509, 2019). "Plasma levels of the proinflammatory cytokine IL-1β and the anti-inflammatory cytokine IL-10 were also elevated in mice with CLP-induced sepsis compared to sham-operated mice (p < 0.001 and p < 0.01 for IL-1β and IL-10, respectively)." (PMID 31792313, 2019). "Comparison of molecules between the control and sepsis groups revealed statistically significant differences, except for IFN-α, IL-1RA, IL-1β, IL-2, IL-6, IL-7, IL-15, LIF, GM-CSF, TNF-α, CCL4, CCL5, and CXCL12." (PMID 31583025, 2019). "Another study has reported elevated levels of IL-1β, IP-10, I-309, and MCP-2 in blood samples from newborns with sepsis induced by a variety of bacterial pathogens compared to healthy babies; all of these cytokines were enhanced in the array analysis." (PMID 31536604, 2019).
Sepsis (continued). "Myocardial mRNA levels of IL-1β, IL-6, IL-18, IP-10, E-selectin and PAI-1 were significantly elevated in RV and LV during sepsis compared to PAB, while Caspase-1 was decreased in septic compared to PAB animals (all p<0.05)." (PMID 31247004, 2019). "In myocardium, TNF and IL-6 were significantly elevated in sepsis, TNF in both ventricles and IL-6 mostly in RV, while IL-1β, IL-18 and C5a were significantly higher in RV compared to LV after PAB (all p<0.05)." (PMID 31247004, 2019). "Because the nature of sepsis is an excessive inflammatory response to infection,we measured serum pro-inflammatory cytokine levels including TNF-α, IL-1β andIL-6." (PMID 30843942, 2019). "In lipopolysaccharide (LPS)-induced sepsis, lung expression of 5-HT7 receptors increases in parallel to the increased expression of TNF-α, IL-1β, and NF-κB." (PMID 31892309, 2019). "During the recurrence and development of sepsis, the release of cytokines shows cascade effect, including the pro-inflammatory factors TNF-α, IL-1β and IL-623,24." (PMID 31432993, 2019). "In the present study, we observed that FX can significantly inhibit the production of inflammatory cytokines IL-6, IL-1β, and TNF-α and promote the sepsis mouse model survival rate from 0% to 40% for the first time." (PMID 31555126, 2019). "NO and proinflammatory cytokines including IL-1β and TNF-α were involved in LPS induced inflammation of macrophages, which mimic the clinical sepsis-induced inflammatory responses." (PMID 31856816, 2019). "We found that the mRNA expressions of TNF-α, IL-1β, and IL-6 were upregulated in MLN DCs and those of IL-1β and IL-6 were augmented in SP DCs by sepsis." (PMID 31323786, 2019). "Monocytes and neutrophils produce IL-1β, tumor necrosis factor-α (TNF-α), and IL-10, cytokines constituting the storm during sepsis." (PMID 30538802, 2018). "Sepsis induces upregulation of multiple proinflammatory genes in the diaphragm, including various proinflammatory cytokines such as TNF-α, IL-1β and IL-6 and there is evidence that these cytokines are involved in sepsis-induced diaphragmatic dysfunction." (PMID 30067847, 2018). "In patients who suffered from sepsis and acute renal failure, continuous veno-venous hemofiltration with dialysis removed TNF-α and IL-1β from systemic circulation." (PMID 29649247, 2018). "Plasma cytokine levels of IL-1β, TNF-α, IL-6, and MCP-1 were markedly increased in patients with sepsis compared to those in healthy control subjects." (PMID 30337925, 2018). "Systemic administration of LPC protects mice against experimental sepsis-induced lethality, enhances bacterial clearance, and inhibits the production of pro-inflammatory cytokines, including TNF-α and IL-1β." (PMID 29755479, 2018). "Under pathological conditions of sepsis, a high concentration of NO can activate the NF-κB signaling pathway and induce proinflammatory cytokines (TNF-α, IL-1β, and others)." (PMID 30498752, 2018). "Then, we detected the expression levels of IL-1β, IL-6 and TNF-α in patients with sepsis and healthy subjects to evaluate the influence of the functional IL-27 SNP on the production of these related cytokines." (PMID 30268141, 2018). "after inducing sepsis by more than 40% (42% in IL-6, 48% in TNF, and 43% in IL-1β levels) (frames (a)-(c))." (PMID 30364002, 2018). "Cytokine changes have been extensively studied in patients with septicemia or after exposure to endotoxin with sequential increases in TNF-α, IL-1β, IL-6, IL-1Ra, and IL-10." (PMID 29149303, 2018). "Sepsis increased the mRNA expression of the inflammatory markers (TNF-α, IL-1β), but also augmented the expression of TGF-β1, a biomarker of immune disorder." (PMID 30108263, 2018). "In severely burned patients with sepsis, plasma levels of endotoxin and cytokines, including TNF-α, IL-1β, IL-6, and IL-8 after CRRT were significantly reduced based on those before the therapy." (PMID 29649247, 2018).